CDH13 (cadherin 13)
Description:
Cadherins are calcium-dependent cell adhesion proteins. They preferentially interact with themselves in a homophilic manner in connecting cells; cadherins may thus contribute to the sorting of heterogeneous cell types. May act as a negative regulator of neural cell growth.
Synonyms: CDHH; P105
Tractability: Antibody: its Gene Ontology location is reachable by antibodies, with high confidence; UniProt places it where antibodies can reach, with medium confidence; UniProt predicts a signal peptide or a membrane-spanning region; the Human Protein Atlas places it where antibodies can reach. PROTAC: its protein half-life has been measured.
Safety:
Unwanted effects reported when the protein is acted on. In parentheses: how it was acted on, where the effect was seen, and who reports it.
diarrhea (source: ClinPGx)
Gene: Protein-coding gene on chromosome 16 (82,626,965 to 83,800,640, forward strand). Ensembl gene ENSG00000140945.
Subcellular location: Cell membrane; Cytoplasm
Subcellular location (Human Protein Atlas): Plasma membrane
Pathways (Reactome):
Cell-Cell communication: Adherens junctions interactions
Gene Ontology:
Molecular function: cadherin binding; lipoprotein particle binding; low-density lipoprotein particle binding; protein binding; adiponectin binding; beta-catenin binding; calcium ion binding; identical protein binding
Biological process: calcium-dependent cell-cell adhesion; endothelial cell migration; homophilic cell-cell adhesion; keratinocyte proliferation; lamellipodium assembly; localization within membrane; low-density lipoprotein particle mediated signaling; negative regulation of cell adhesion; negative regulation of cell population proliferation; positive regulation of calcium-mediated signaling; positive regulation of cell migration; positive regulation of cell-matrix adhesion; positive regulation of endothelial cell proliferation; positive regulation of positive chemotaxis; positive regulation of smooth muscle cell proliferation; positive regulation of transcription by RNA polymerase II; Rac protein signal transduction; regulation of endocytosis; regulation of epidermal growth factor receptor signaling pathway; Rho protein signal transduction; sprouting angiogenesis; adherens junction organization; cell migration; cell morphogenesis; cell-cell adhesion mediated by cadherin; and 3 more
Cellular component: caveola; cytoplasm; extracellular exosome; extracellular matrix; extracellular region; focal adhesion; neuron projection; plasma membrane; adherens junction; catenin complex; external side of plasma membrane; membrane
Genetic constraint (gnomAD): Loss-of-function variants: 16 observed, 53.24 expected, observed/expected ratio (o/e) 0.3, 90% interval 0.2 to 0.46. The synonymous counts are far from expectation, so gnomAD's model fits this gene poorly and the ratio says little. Missense variants: 918 observed, 843.48 expected, observed/expected ratio (o/e) 1.09, 90% interval 1.03 to 1.15. Synonymous variants: 446 observed, 338.8 expected, observed/expected ratio (o/e) 1.32, 90% interval 1.22 to 1.42.
Homologues: Orthologues: chimpanzee CDH13 (99% identical), macaque CDH13 (98% identical), guinea pig CDH13 (94% identical), dog CDH13 (94% identical), mouse Cdh13 (94% identical), pig CDH13 (93% identical), rat Cdh13 (93% identical), rabbit CDH13 (86% identical), tropical clawed frog cdh13 (71% identical), zebrafish cdh13 (57% identical). Paralogues in human: CDH2 (41% identical), CDH4 (39% identical), CDH1 (36% identical), CDH3 (34% identical), CDH15 (31% identical), CDH18 (26% identical), CDH23 (26% identical), CDH20 (25% identical), CDH24 (25% identical), CDH26 (25% identical), CDH7 (25% identical), CDH8 (25% identical), and 21 more.
Diseases named in the same sentence as CDH13 in open-access papers:
CDH13 is named in the same sentence as 186 diseases in open-access papers, as found by Europe PMC text mining. Sharing a sentence is not in itself a finding about the gene and the disease. The quoted sentences say what the papers report.
breast cancer (46 papers, 2007 to 2025). A primary or metastatic malignant neoplasm involving the breast. "The univariate Cox regression demonstrated that high levels of CDH13 were an independent risk factor for poor overall survival (OS) in breast cancer patients." (PMID 36315446, 2022). "As we have inferred, studies of both tissue and serum showed a significant association between CDH13 methylation and breast cancer (OR = 16.45, 8.21 by random effects model, respectively)." (PMID 27153114, 2016). "Here, we conducted a meta-analysis of the risk and prognosis of CDH13 methylation in relation to breast cancer diagnosis." (PMID 27153114, 2016). "Here, we conducted a meta-analysis to explore the association between CDH13 methylation and breast cancer." (PMID 27153114, 2016). "To explore the association between CDH13 promoter methylation and breast cancer risk and prognosis, we systematically integrated published articles to investigate the diagnostic performance of the CDH13 methylation test for breast cancer." (PMID 27153114, 2016). "In conclusion, this meta-analysis of the article data provides strong evidence that the methylation status of the CDH13 promoter is strongly related to breast cancer risk." (PMID 27153114, 2016). "Methylation of HIN-1, RASSF1A, RIL and CDH13 in breast cancers was associated with clinical characteristics, but only RASSF1A methylation was associated with time to first recurrence and overall survival." (PMID 22695491, 2012). "A high prevalence of PGR, HSD17B4, and CDH13 methylation has been associated with HER-2/neu-positive breast cancer." (PMID 17764565, 2007). "For this reason, effective screening and early, accurate detection of aberrantly methylated CDH13 promoter region could be used as a promising diagnostic and prognostic marker for various malignancies, including breast cancer." (PMID 38926485, 2024). "The methylation site, cg02263260, located in the promoter region of CDH13 might be important in assessing breast cancer risk and prognosis." (PMID 33407434, 2021). "However, the diagnostic role of the methylation status of the CDH13 gene in breast cancer lacks quantitative assessment." (PMID 27153114, 2016). "The methylation status of CDH13 promoter was strongly associated with breast cancer risk." (PMID 27153114, 2016). "Therefore, CDH13 promoter methylation is likely to be linked to the risk of breast cancer and may have limited prognostic value for breast cancer patients." (PMID 27153114, 2016). "Early studies indicated that CDH13 gene is frequently methylated in breast cancer, leading to downregulation of T-cadherin expression." (PMID 40230838, 2025). "CDH13 is a known tumor suppressor gene, and its promoter is methylated in breast cancer patients and other cancers as well." (PMID 35615145, 2022). "Cadherin T (cadherin 13), encoded by the CDH13 gene, is a member of cadherin superfamily; in ductal carcinoma in situ and adjacent invasive ductal carcinoma breast cancer patients, aberrant methylation of the CDH13 promoter was a frequent early event." (PMID 34209857, 2021). "We show that Star-PAP and PIPKIα together regulate 3′-end processing and expression of pre-mRNAs encoding key anti-invasive factors (KISS1R, CDH1, NME1, CDH13, FEZ1, and WIF1) in breast cancer." (PMID 29203642, 2018). "Another seven genes (CDH13, CDH7, CTNNA2, ERBB4, GRIK1, PCDH15, and TCF7L2) were reported as associated with the breast cancer by recent GWA studies." (PMID 28615668, 2017). "To validate the results of the meta-analysis, we collected the data on the CDH13 methylation status, and clinical characteristics from the breast cancer samples of the TCGA project." (PMID 27153114, 2016). "In this study, we set out to explore the relationship between CDH13 promoter methylation and breast cancer survival using data extracted from the TCGA project." (PMID 27153114, 2016). "As predicted, the same result was found in the data of TCGA project of CDH13 methylation in breast cancer." (PMID 27153114, 2016).
breast cancer (continued). "Future studies are needed that collectively explore the possible roles of CDH13 methylation in breast cancer." (PMID 27153114, 2016). "Aberrant methylation of the CDH13 gene has been reported in many cancers, including non-small cell lung cancer, breast cancer, gastric cancer, and colorectal carcinoma." (PMID 27578166, 2016). "The expression level of CDH13 was found to be significantly reduced in breast cancer specimen and breast carcinoma cell lines." (PMID 27884161, 2016). "Taken together, the results of this systematic review indicate a credible relationship between CDH13 methylation and breast cancer." (PMID 27153114, 2016). "Our results revealed that the frequency of CDH13 promoter methylation in breast cancer tissue/serum was significantly higher than in normal tissue/serum." (PMID 27153114, 2016). "Although CDH13 methylation in breast cancer has been reported as an effective biomarker for diagnosis, the results differ dramatically between different research studies." (PMID 27153114, 2016). "Current studies have highlighted the role of CDH13 as a tumor suppressor in lung cancer, breast cancer and malignant melanoma, and so on." (PMID 24466011, 2014). "The closely related basal-like tumors also had decreased RASSF1A methylation (p = 0.052) when compared with other breast cancer subtypes, while the luminal A tumors tended to have a reduced CDH13 methylation (p<0.03)." (PMID 22701537, 2012). "On the other hand, the high frequency of methylation in MSH6, PAX5, PAX6 and CDH13 was shared between male and female breast cancer." (PMID 22765268, 2012). "CDH13 has been reported to be highly methylated in HER2/neu-positive breast cancers, which comprise 20% to 30% of invasive breast carcinomas." (PMID 22695491, 2012). "Our results indicate that RIL, HIN-1, RASSF1A, CDH13, and RARβ2 are also frequently methylated both in primary breast cancers and in lymph node metastases." (PMID 20642860, 2010). "Our previous study demonstrated that 5 putative tumor suppressor genes (HIN-1, RASSF1A, RIL, CDH13, RARβ2) were frequently methylated in primary breast cancers." (PMID 20642860, 2010). "Methylation of RIL, HIN-1, RASSF1A, and CDH13 exhibited a positive correlation between breast cancer and normal tissues." (PMID 17764565, 2007). "SMART App has breast cancer samples of all subtypes, of which TNBC represents the smallest subtype.ST08 hypomethylated promoter of CDH13 leading to its upregulation.CDH13 is a known tumor suppressor gene, and its promoter is methylated in breast cancer patients and other cancers as well." (PMID 36474139, 2022). "The down-regulation of CDH13 may be related to tumour invasiveness in EC, as it was observed in breast cancer where cells transfected with CDH13 were less invasive." (PMID 36232772, 2022). "Interestingly, CDH13 (TSG) is hypermethylated in breast cancer patients, and the drug ST08 induced hypomethylation and tumor suppressor expression." (PMID 36474139, 2022). "Moreover, in breast cancer, CDH13 methylation was highly correlated with the down-regulation of estrogen and progesterone receptors." (PMID 33407434, 2021). "Therefore, an integrated analysis with unbiased conclusions was conducted to examine the relationship between CDH13 methylation and breast cancer." (PMID 27153114, 2016). "Recent studies have reported that CDH13 is an important tumor suppressor in breast cancer patients." (PMID 27153114, 2016). "For example, RASSF1A, CDH13 and RARβ have been reported to be frequently methylated in breast cancer (average frequency of 71 %, 49 % and 21 % respectively), which is similar to our results of 64 %, 51 % and 19 % methylation in both ipsilateral and contralateral pairs respectively." (PMID 26452468, 2015).
breast cancer (continued). "Examples of other hypermethylated genes used to predict poor clinical prognosis include CDKN2A in colorectal cancer, RASSF1A and APC in breast cancer, the apoptosis-associated gene DAPK1 in lung and head and neck cancers, and CDKN2A, RASSF1A, cadherin 13 (CDH13) and APC in stage I NSCLC." (PMID 25473433, 2014). "In addition, we observed associations between CDH13, SFRP1, and RASSF1A methylation and breast cancer subtypes and between SFRP1 methylation and patient's age." (PMID 22701537, 2012). "Tumors from 193 patients with early stage breast cancer were used to analyze promoter methylation of the RIL, HIN-1, RASSF1A and CDH13 tumor suppressor genes for association with known predictive and prognostic factors and for impact on time to first recurrence and overall survival." (PMID 22695491, 2012). "Hence, the methylation status of CDH13 could be used as a potential biomarker for breast cancer diagnosis for either tissue or serum samples." (PMID 27153114, 2016). "Thus CDH13 hypermethylation may contribute to the distinct molecular alterations hypothesized for AA and EA tumors that may play a role in the early onset of breast cancer that lacks ER expression." (PMID 22701537, 2012). "In breast cancer, BRCA1 has been reported as a target of UHRF1-mediated methylation, while in non-small-cell lung cancer, RASSF1, CYGB, and CDH13 have been identified as UHRF1-regulated methylation targets." (PMID 41373864, 2025). "CDH13 is highly methylated in cancers such as CML, non-small cell lung cancer, and breast cancer, resulting in a significant decrease in its expression level and the loss of biological functions of oncogenes." (PMID 39179585, 2024). "Baseline characteristics of eligible studies evaluating CDH13 methylation and OS or DFS in breast cancer patients." (PMID 27153114, 2016). "The five most frequently methylated TSGs (RASSF1, APC, CDH13, GSTP1, and CDKN2B) were the same in all groups of breast cancer and, with the exception of CDKN2B, were involved in other tumors from LS patients, too, although with variable frequencies." (PMID 22691310, 2012). "The most frequently hypermethylated genes (MSH6, CDH13, PAX5, PAX6 and WT1) were similar for male and female breast cancer." (PMID 22765268, 2012). "Several tumor suppressor genes are silenced by promoter hypermethylation in breast cancers including HIN-1, RASSF1A, RIL, and CDH13, among others." (PMID 22695491, 2012). "Methylation is involved in the development of female breast cancer, with frequent methylation of PAX6, BRCA2, PAX5, WT1, CDH13 and MSH6 in ductal carcinoma in situ and invasive ductal cancer." (PMID 22765268, 2012). "Low expression of CDH13 has been observed in many cancers, including non-small cell lung cancer, nasopharyngeal cancer, esophageal cancer, ovarian cancer, CML, acute myeloid leukemia, and breast cancer." (PMID 39179585, 2024). "Particularly, the negative association between the genes CDH2, CDH3, CDH11, CDH13, CDH18 and NAT1 N-acetylation activity supports observations of high NAT1 expression in breast cancer and increased metastasis." (PMID 35046826, 2021). "O-mannosylation of numerous members of these protein families has been recently demonstrated in simplified human breast cancer cells, but, with the exception of CDH13, not yet from native tissues." (PMID 27812179, 2016). "Furthermore, Feng and colleagues (2007) analyzed the methylation of multiple genes in breast cancer using bisulfite pyrosequencing and found that RASSF1 was methylated in 58 % of breast tumors, CDH13 in 44 % and RARB in 17 %." (PMID 27065772, 2016). "Methylation-sensitive high-resolution melting was used to screen promoter methylation in a panel of 13 genes reported as methylated in breast cancer (RASSF1A, TWIST1, APC, WIF1, MGMT, MAL, CDH13, RARβ, BRCA1, CDH1, CDKN2A, TP73, and GSTP1) in 29 tumour pairs (16 ipsilateral and 13 contralateral)." (PMID 26452468, 2015).
breast cancer (continued). "Interestingly, genes with frequent methylation in male breast cancer (MSH6, CDH13, PAX5, PAX6 and WT1) were also very commonly methylated in female breast cancer." (PMID 22765268, 2012). "The most frequently methylated genes were RASSF1 (65%), APC (43%), CDH13 (35%), GSTP1 (17%), and CDKN2B (17%), and the pattern was quite similar in breast carcinomas from mutation carriers, non-carriers and sporadic ductal cases." (PMID 22691310, 2012). "Our previous study revealed that five of 12 tumor suppressor genes, RIL, HIN-1, RASSF1A, CDH13, and RARβ2, were frequently methylated in primary breast cancers but not in normal breast tissue." (PMID 20642860, 2010). "The results from the analysis of six breast cancer cell lines and two normal breast epithelial cell samples indicated that 7 of 12 genes (RIL, HIN-1, RASSF1A, ARHI, CDH13, RARβ2, and NKD2) were densely methylated (marked bold) in cancer cell lines but not in normal breast epithelial cell lines." (PMID 17764565, 2007). "Five of them (RIL, HIN-1, RASSF1A, CDH13, and RARβ2) were frequently methylated in breast cancers (57%, 49%, 58%, 44%, and 17%, respectively) but not the normal breast (0–4%)." (PMID 17764565, 2007). "Our data confirmed that RIL, HIN-1, RASSF1A, CDH13, and RARβ2 were frequently methylated in breast cancers but not in normal breast tissues." (PMID 17764565, 2007). "Five tumor-suppressor genes (RASSF1A, RIL, HIN-1, CDH13, and RARβ2) were frequently methylated in breast cancer tissues (the positive rate ranged from 17% to 58%) but not in normal breast tissues (the positive rate ranged from 0% to 4.5%)." (PMID 17764565, 2007). "Consequently, many researchers have tried to explore the role of CDH13 methylation and the epigenetics of other genes in the prognosis and early detection of breast cancer, as well as the differentiation between malignant and non-malignant lesions." (PMID 27153114, 2016). "As predicted, patients without CDH13 methylation live almost the same time as patients with CDH13 methylation (HR = 1.41, 95% CI = [0.82; 2.48], p = 0.210), suggesting that CDH13 methylation does not decrease the survival rate in patients with breast cancer." (PMID 27153114, 2016). "However, CDH13 methylation is not prognostic for breast cancer patients." (PMID 27153114, 2016). "However, CDH13 promoter methylation was not significantly related to the OS and DFS of breast cancer." (PMID 27153114, 2016). "However, CDH13 promoter methylation was not significantly related to the OS and DFS of breast cancer and may have limited prognostic value for breast cancer patients." (PMID 27153114, 2016).